HMGN5 (high mobility group nucleosome binding domain 5)
Diseases named in the same sentence as HMGN5 in open-access papers (continued):
Sharing a sentence is not in itself a finding about the gene and the disease.
glioblastoma (2 papers, 2018 to 2020). The most malignant astrocytic tumor (WHO grade IV). "In this study, we investigated the expression level of HMGN5 in glioblastoma tissues and cell lines." (PMID 32596388, 2020). "Our findings demonstrated that HMGN5 was involved in regulating proliferation, apoptosis, migration, and invasion of glioblastoma cells." (PMID 32596388, 2020). "In the present study, we found that the expression of HMGN5 is significantly higher in high-grade glioblastoma tissues than in low-grade samples." (PMID 32596388, 2020). "To further investigate the function of HMGN5 in glioblastoma, we knocked down HMGN5 in two glioblastoma cell lines U87 and U251." (PMID 32596388, 2020). "All the data above were consistent with previous research that HMGN5 promoted proliferation and inhibited apoptosis of glioblastoma." (PMID 32596388, 2020). "Then, FACS was performed to assess the role of HMGN5 in the cell cycle and cell apoptosis of glioblastoma." (PMID 32596388, 2020). "CCK8 assays were used to investigate the effect of the interference of HMGN5 on glioblastoma cell proliferation, and the results indicated that the proliferation capacity was suppressed while being transfected with HMGN5-siRNA 48 hours." (PMID 32596388, 2020). "To clarify the function of HMGN5 in glioblastoma, we knocked down HMGN5 in U87 and U251 glioblastoma cells via siRNA." (PMID 32596388, 2020). "The result of the JC-1 assay indicated that HMGN5 was involved in early apoptosis in glioblastoma cell lines." (PMID 32596388, 2020). "Firstly, we demonstrated that the proliferative capacity of glioblastoma cells was decreased as HMGN5 was knocked down in vitro and in vivo." (PMID 32596388, 2020). "The effects of HMGN5 on proliferation, apoptosis, migration, and invasion of glioblastoma cells were observed by RNA interference to silence this gene in vitro." (PMID 32596388, 2020). "In glioblastoma, although previous research showed that the overexpression of HMGN5 promoted proliferation and survival of glioblastoma cells, the mechanisms underlying the oncogenic role of HMGN5 remained unclear." (PMID 32596388, 2020). "To summarize, our data validate that HMGN5 has a high expression in glioblastoma and functions as an oncogene." (PMID 32596388, 2020). "In this study, we confirmed that high-grade glioblastoma usually had higher expression of HMGN5 than lower grade glioblastoma, which suggested that a high level of HMGN5 is correlated to the malignancy of glioblastoma." (PMID 32596388, 2020). "RT-PCR and western blot were performed to detect the mRNA and protein levels of HMGN5 in tissues and glioblastoma cell lines (SNB19, A172, U87, LN229, U251, and LN308)." (PMID 32596388, 2020). "While in our research, we found that HMGN5-siRNA arrested the cell cycle at the G1/G0 phase along with the decreased expression of Cyclin D1 and p21 protein in glioblastoma cells." (PMID 32596388, 2020). "The results demonstrated that HMGN5 was involved in the regulation of proliferation and apoptosis, migration, and invasion of glioblastoma cells." (PMID 32596388, 2020). "Also, HMGN5 knockdown regulates glioblastoma cell growth, invasion, and migration via the AKT and MAPK pathway." (PMID 32596388, 2020). "Taken together, we speculated that HMGN5 in glioblastoma cells could regulate Bcl-2, Bax, Cyclin D1, p21, MMP-2, and MMP-9 to play an oncogenic role partly via the PI3K/AKT pathway." (PMID 32596388, 2020). "As expected, HMGN5-siRNA induced mitochondrial pathway apoptosis in glioblastoma cells." (PMID 32596388, 2020). "To investigate whether HMGN5 regulates the malignant behavior of glioblastoma cells via AKT and MEK oncogenic cascades, we examined AKT and ERK1/2 proteins." (PMID 32596388, 2020). "Moreover, MMP-2 and MMP-9, the members of the metalloproteases family, which were frequently involved in glioblastoma invasiveness, were downregulated along with the reduction of HMGN5 in glioblastoma cells." (PMID 32596388, 2020).
glioblastoma (continued). "Taken together, our research reveals that HMGN5 might be an efficient target for glioblastoma-targeted therapy." (PMID 32596388, 2020). "Our findings suggest that HMGN5 plays an important role in the initiation and progression of glioblastoma, which may provide us with an efficient target for glioblastoma-targeted therapy." (PMID 32596388, 2020). "HMGN5-siRNA inhibited the proliferation and increased the apoptosis rate of glioblastoma cells." (PMID 32596388, 2020). "Moreover, whether HMGN5 is related to the aggressiveness and chemoresistance of glioblastoma needs further elucidation." (PMID 32596388, 2020). "Expectably, our research showed that knockdown of HMGN5 downregulated the expression of p-MEK1 and p-ERK1/2 in glioblastoma cells." (PMID 32596388, 2020). "And our findings indicated that silencing HMGN5 downregulated p-PI3K and p-AKT in glioblastoma cells." (PMID 32596388, 2020). "Our data proposed HMGN5 as a critical molecule which is involved in the regulation of malignant behavior as well as in the PI3K/AKT and MAPK pathway in GBM cells, suggesting that this protein might be a possible target for glioblastoma-targeted therapy." (PMID 32596388, 2020).
urothelial bladder cancer (2 papers, 2018 to 2020). "Studies showed that the PI3K/AKT pathway was targeted by HMGN5 in human urothelial bladder cancer." (PMID 32596388, 2020). "Knockdown of HMGN5 could increase the chemosensitivity of human urothelial bladder cancer cells to cisplatin by targeting PI3K/Akt signaling." (PMID 29710817, 2018).
emphysema (1 paper, 2023). "HMGN5 modulates cellular transcription and, in a murine model, mutations in HMGN5 are associated with a lung function phenotype on pulmonary function tests as well as an emphysema-like phenotype." (PMID 36726148, 2023).
neuroblastoma (1 paper, 2020). Neuroblastoma (NB) is the most common solid, extracranial childhood tumor. "In the mouse neuroblastoma cell line N1E-115, the mRNA encoding HMGN5 localizes to growth cones of both neuron-like cells and of hippocampal neurons, where it has the potential to be translated, and that HMGN5 can be retrogradely transported into the nucleus along neurites." (PMID 31936777, 2020).
neurosyphilis (1 paper, 2017). Infection of the brain or spinal cord by Treponema pallidum. "For instance, mRNA NM_030763, whose encoding product is the HMGN5 protein, was significantly decreased in the neurosyphilis patients." (PMID 29167762, 2017).
tumor (21 papers, 2012 to 2025). "A number of the identified tumour-associated antigens are known to signal via this cascade, HMGN5, TFG, MAEL, SOX15 and Dicckopf-1, the latter of which has been investigated in numerous other biomarker signatures and like TFG interacts via the Wnt co-receptor LRP6." (PMID 34728792, 2022). "Tumor suppressive miR-183-3p directly regulates the expression of HMGN-5 thereby regulating PCa tumorigenesis and development." (PMID 38705879, 2024). "Overexpression of HMGN5 is an important factor in tumor infiltration and metastasis, making it possible to apply specific inhibitors and targeted drugs to impede HMGN5’s pro-tumor effect and exert anti-tumor efficacy." (PMID 39591457, 2024). "HMGN5 not only binds to nucleosomes to regulate the chromosomal structure and function, thus affecting DNA replication and repair but also plays a role in tumor development, with its overexpression being crucial in tumor cell invasion and metastasis." (PMID 36568211, 2022). "HMGN5 can regulate expression of PI3Kp85α and p-Akt, and results in tumor cells having malignant potential." (PMID 29710817, 2018). "Beyond that, STAT3 and HMGN5 also colocalize in MDA-MB-231 TNBC tumor spheres." (PMID 40507264, 2025). "Since MDA-MB-231 xenografts with knockdown of HMGN5 exhibited reduced tumor growth, this suggests that the interaction between STAT3 and HMGN5 could be used as a future target for treatment." (PMID 40507264, 2025). "HMGN5 interacts with Hsp27 to promote tumor growth in a human BC xenograft model in nude mice." (PMID 32315283, 2020). "Studies showed that knockdown of HMGN5 could sensitize several tumor cells to radiotherapy or some chemotherapeutic drugs." (PMID 32596388, 2020). "Furthermore, the chemokine CCL2 and nucleosome-binding protein HMGN5 were increased significantly since CCL2 plays a key role in tumor inflammation and HMGN5 might be the important regulators of gene expression in cells." (PMID 35774500, 2022). "Finally, the dynamic effects of HMGN5 and Hsp27 on tumor growth were investigated in nude mice." (PMID 32315283, 2020). "Analysis of gene expression of LUAD and matched adjacent non-tumor tissues from three cohorts showed consistent up-regulation of HMGN1 in LUAD across all cohorts, with HMGN5 down-regulated in two of them." (PMID 38710740, 2024). "Knocking down HMGN5 decreased the expression of Bcl-2, Cyclin D1, MMP-2, and MMP-9 and increased the expression of Bax and p21 which is related to the malignant phenotype of tumor proliferation, migration, and invasion." (PMID 32596388, 2020).
cancer (16 papers, 2012 to 2025). A tumor composed of atypical neoplastic, often pleomorphic cells that invade other tissues. "HMGN5, implicated in embryonic gene regulation and exhibiting oncogenic properties in several cancers, shows a tendency toward upregulation in MB." (PMID 41198629, 2025). "There has been growing evidence that aberrant expression of HMGN5 is associated with malignant neoplasm development and progression." (PMID 32596388, 2020). "High-mobility group nucleosome-binding domain 5 (HMGN5) is overexpressed in many cancers and could cause carcinogenesis in BC." (PMID 32315283, 2020). "Our findings suggest that functional RNA-RNA interactions between coding and non-coding molecules—an emerging theme in cancer regulation—upregulate HMGN5 protein levels, explaining why HMGN5 RNA interference phenocopies lncMB3 targeting effects." (PMID 41198629, 2025). "The results showed that compared to para-cancerous tissues, the mRNA expression of all members of the HMG family was higher in most cancers except for HMGN5 which showed a consistently low expression across most cancer tissues." (PMID 36568211, 2022). "Lastly, some genes (HMGN5, IRS1, PHGDH, MXRA5, GOLIM4, and SFRP2) are associated with the development of multiple cancer types." (PMID 33924951, 2021). "Several nuclear proteins also appeared to be associated through correlations with the increased abundance of the two trypsinogens, particularly HMGN5, whose involvement in nucleosomal binding and transcriptional activation in cancers has been well documented." (PMID 33207594, 2020). "However, HMGN5 protein levels dropped by ∼80% upon lncMB3 KD, consistently with HMGN5 recognised oncogenic activity in various cancers." (PMID 41198629, 2025). "Studies showed that HMGN5 might promote migration and invasion of several types of cancer via regulating MMPs." (PMID 32596388, 2020). "Many of the validated genes bound by ZNF322A such as HMGN5, GATA6, CCAR1 and ELK4, were found to be involved in tumorigenesis in other cancers, further supporting the oncogenic role of ZNF322A." (PMID 30258097, 2019). "The nucleosome binding protein 1 (HMGN5/NSBP1) is a member of the HMGN protein family and is highly expressed in several kinds of cancer." (PMID 22420896, 2012).
HMGN5 also shares sentences with these, for which no sentence is quoted: hepatocellular carcinoma (3 papers); gastric cancer (2); lung carcinoma (2); meningioma (2); renal carcinoma (2); adenocarcinoma (1); breast tumor (1); cardiomyopathy (1); Colon cancer (1); esophageal squamous cell carcinoma (1); infection (1); kidney cancer (1); lymph node metastasis (1); medulloblastoma (1); non-small cell lung carcinoma (1); Obesity (1); ovarian carcinoma (1); squamous cell carcinoma (1).